CXCL9 (C-X-C motif chemokine ligand 9)
Diseases named in the same sentence as CXCL9 in open-access papers (continued):
Sharing a sentence is not in itself a finding about the gene and the disease.
infection (continued). "Together our data suggest that IMs play an important role in recruiting CD4+ T cells to the foci of infection via the CXCL9/CXCR3 axis and provide an important source of IL-12 for maintaining Th1 cells." (PMID 37733817, 2023). "CXCL2 and CXCL9 in chemokine were 957.6-fold and 128.5-fold upregulated in the spleen at 48 h of infection; by 96 h, the higher expression levels were CsCCL21.2, TroCCL4.2, and CsCCK1." (PMID 37888440, 2023). "Some up-regulated genes at 21 dpi (e.g., Ltf, Cxcl9, Pglyrp1, Prg2, Cxcl13, Cxcl3, Ccl9, Ccl19, Krt5, Krt14, Krt15, Krt17, and Slpi) were also identified in a previous infection study by using H1N1(PR8)." (PMID 38005876, 2023). "Of note, infection with SARS-CoV-2 induces interferon-stimulated chemokines such as Cxcl9 and Cxcl10 similar to infected human lung." (PMID 34957381, 2022). "Another gene significantly upregulated by infection with rBCG-LTAK63 compared to BCG is the IFN-induced monokine-encoding gene, CXCL9, that is induced in response to IFN-γ and induces inflammation together with recruitment of activated lymphocytes." (PMID 35746439, 2022). "Infection led to robust induction of chemokine and interleukin genes, including Il1b, Il6, Ccl2, Ccl3, Ccl4, Ccl7, Cxcl1, Cxcl2, Cxcl5, Cxcl9, and Cxcl10, and related receptor genes, including Ccr1, Ccr4, Ccr5, Ccr5, Ccr7, Cxcr2, Cxcr5, Il1r2, and Il1rn." (PMID 35487885, 2022). "Migration of NKT cells to sites of infection and inflammation is mediated by chemokines such as CXCL9." (PMID 35656032, 2022). "Two immune genes were observed in the gene expression analysis, IL-10 and CXCL9, to be lower during the repeat infection compared to baseline." (PMID 36299763, 2022). "In our study, we observed lower concentrations of CXCL9/MIG in patients with severe Delta infection." (PMID 36012323, 2022). "Although there was some overlap in the mediators enriched in infections with either virus, mediators associated with viral clearance, such as CXCL10, CXCL9, CCL11, and CCL2, were preferentially decreased in RSV infection." (PMID 35406717, 2022). "When comparing the samples from the patients with different infection severities of the same genetic variant, we noted differences in the CCL7/MCP-3, CXCL9/MIG, and CXCL10/IP-10 concentrations." (PMID 36012323, 2022). "We detected CXCL10 and CXCL9 surges during primary infection to mirror NK cell, neutrophil and monocyte influxes." (PMID 35590057, 2022). "CXCL9 enables migration of more circulating TM cells to sites of infection, enhancing the activation of local DCs and NK cells and the establishment of an IFNγ-driven antiviral state providing broad protective immunity against unrelated microbial pathogens." (PMID 34516896, 2021). "A previous study documented that L. braziliensis-infected macrophages from CL patients produce more CXCL9 than macrophages obtained from individuals with subclinical infection or cells from HS." (PMID 34691019, 2021). "In human CL caused by L. braziliensis, macrophages from CL patients produce high levels of CXCL9 compared to cells obtained from individuals with subclinical infection or healthy subjects." (PMID 34691019, 2021). "Another cytokine that demonstrates robust levels from an early infection stage is CXCL9, responsible for CD4+ lymphocyte recruitment." (PMID 33746980, 2021). "Alternative potential biomarkers of bTB disease progression include IL-17A, also of the Th17 subset, and CXCL9 due to the observed increase as infection progresses with additional correlations to lesion severity." (PMID 33746980, 2021). "At 24 hr post-infection, we observed significant increases in WT production of Il27, Cxcl10, and Cxcl9, which were diminished in Mincle-/- cells." (PMID 34320039, 2021). "IL-22 can act synergistically with TNFα in response to infection-promoting chemokine expression (including CXCL9, CXCL10 and CCL5) by human keratinocytes." (PMID 34207946, 2021).
infection (continued). "The CXCL9 network is connected with ascending infection, while the CXCL11 network is distant and disconnected, which indicates a more favorable host response." (PMID 32127796, 2020). "One example was an infection-induced interaction between myeloid cells and T cells via Cxcl9 and Cxcr3." (PMID 32461220, 2020). "(E) CXCL9 ELISA of skin lysates of primed or naïve wt mice after 5 days of (re-)infection (n: eight biological replicates representing two independent experiments)." (PMID 32639232, 2020). "While the expression of Cxcl10 and Cxcl11 in C57BL/6 and IL-6−/− mice was similar, it was significantly increased for Cxcl9 in IL-6−/− mice on day 14 and tended to remain higher compared to wild type animals in the further course of infection." (PMID 33375150, 2020). "Upon infection, Cxcl9 transcripts (shown in brown) localized within the lamina propria in an IFNγR-dependent manner, and not along the epithelial border, consistent with a non-epithelial source of CXCL9." (PMID 31776431, 2020). "The cytokines IL‐8 and CXCL‐9 were measured in supernatants of neutrophil 90 minutes after infection with L. (V.)braziliensis obtained from DL or CL patients." (PMID 30815888, 2019). "While IL-1α and IL-1β levels in WT and IL-1R−/− mice were similar, levels of IL-6, IL-12p70, IFN–γ, CCL2, CCL3, and CXCL9 were significantly lower in IL-1R−/− mice compared with wild-type mice following infection with P1/7 (p < 0.05)." (PMID 31262357, 2019). "CXCL9 and CXCL11 were negatively correlated with CD4+ T-cell count at 1-year-infection point (CXCL9, r = − 0.5692, p = 0.0007; CXCL11, r = − 0.3741, p = 0.0349)." (PMID 31836011, 2019). "Our data demonstrate that CXCL11 is significantly up-regulated during PHI, positively correlating with CXCL9 and CXCL10, and negatively associated with CD4+ T-cell count at 1-year-infection point." (PMID 31836011, 2019). "The transcripts specific for CXCL9 were also significantly higher in lung of KO mice 48 h post-infection." (PMID 30333823, 2018). "We also observed a significant increase in the expression of CXCL9 48 h post-infection compared to WT mice." (PMID 30333823, 2018). "The infection classifier based on the combination of CXCL9 and CXCL10 serum levels was identified as the best model comprising the minimum set of biomarkers and allowing an accurate infection classification." (PMID 29988532, 2018). "The cutoff serum concentration values for prediction of infection etiology with both sensitivity and specificity of 1 was 17.5 pg/ml for CXCL9 and 4.5 pg/ml for CXCL10." (PMID 29988532, 2018). "To understand the role of CD169+ cells in the recruitment of effector T cells to the infection site, we measured the CXCL9 and CXCL10 levels in BAL fluid from DT-treated WT and CD169-DTR mice after RSV infection." (PMID 28751894, 2017). "Out of the 11 evaluated cytokines only 3, i.e. IL-1β, IL-8 and CXCL9, showed highly increased expression levels in biopsies collected at acute stage of infection when compared to biopsies collected at the convalescent stage." (PMID 28319200, 2017). "The levels of MIP1α/Ccl3, IL-1, and IFNγ-inducible factors, such as ICAM-1, IP10/Cxcl10 and Cxcl9 were all increased in the chronic phase of the infection." (PMID 28787450, 2017). "During an infection with another alphaherpesvirus, HSV-1, in mice, it has been reported that CCL3 attracts NK cells, CCL2 recruits monocytes, and CCL5 recruits monocytes, NK cells, and PMNs while CXCL9 recruits T-cells to the sites of infection." (PMID 28241864, 2017). "Infection of H3N2 and H1N1 viruses causes the upregulation of IL-6, CXCL9, and CXCL10 in cultured human umbilical vein endothelial cells." (PMID 28399143, 2017). "An efficient antiviral response induces the recruitment of RSV-specific CD4+ and CD8+ T cells to the infection site by the CXCL9 and CXCL10 chemokines, which are induced by IFNs and the chemokine receptor CXCR3." (PMID 28751894, 2017).
infection (continued). "The prominent and sustained expression of CXCR3 on infiltrating CD19 B cells over the course of infection is consistent with the high-level detection of its ligands CXCL9 and CXCL10 in brain homogenates using ELISA." (PMID 27207308, 2016). "MO-DCs emerge at day 5 and peaked at day 7 post infection with PbA, which coincides with the expression of CXCL9 and CXCL10, and other inflammatory mediators in the CNS." (PMID 27808089, 2016). "This was despite increased expression of T-cellchemoattractant Cxcl9 and Cxcl10 in M-TNFR1 KO mice 3–5weeks post-infection, likely linked to the increased neutrophil population in thesemice." (PMID 26931771, 2016). "In this study, total spleen cells were shown to secrete TNF-α, IFN-γ, IL-6, IL-10, CCL3, and CXCL9, suggesting an activation of splenic cells during the infection and a polarization towards a Th1 response." (PMID 27905502, 2016). "Upon TBwt infection, several type II ISGs (CXCL9, CXCL10, CXCL11 and IDO) exhibited varying degrees of activation at 24 h post infection in accordance with previous reports." (PMID 27387064, 2016). "Infection clearance in resistant mice requires Th1 adaptive responses mediated by the IFNγ-stimulated chemokines CXCL9, CXCL10, and CXCL11 acting in a CXCR3 dependent manner." (PMID 25643352, 2015). "For example, low-level expression of CXCL9 was described in IFNγ-/- mice following infection with vaccinia virus." (PMID 25643352, 2015). "Kupffer cells release substantial amounts of MIG/CXCL9 early following infection with B. burgdorferi, suggesting that a chemotactic gradient facilitates recruitment and interaction of CXCR3+ NKT cells with CD1d+ Kupffer cells." (PMID 26074921, 2015). "Using a mouse model of enteric pathogen infection with both wild type mice and genetic knockouts, we showed that the chemokine CXCL9 has direct antimicrobial activity against pathogen infection." (PMID 25643352, 2015). "Post albendazole and/or praziquantel treatment, the cellular release of IL-10, IL-33, MIP3-α/CCL20 and MIG/CXCL9 lessened significantly in all children infection groups." (PMID 25698903, 2015). "While the authors attributed these findings to increased T cell homing to site of infection, an alternative or additional interpretation, given our current results, is the attendant increase in innate defense mediated by IFNγ-stimulated CXCL9 release." (PMID 25643352, 2015). "The gross pathological differences in C. rodentium-infected mice upon CXCL9 depletion suggested a worsened immunopathological response to infection, which correlated with increased bacterial load." (PMID 25643352, 2015). "The results were consistent with mRNA findings, as large amounts of the CC chemokines CCL3, 4, 5, and 7 and, particularly, of the CXC chemokines CXCL9, 10, and 11 were observed 24 and/or 72 h after the infection of MP with MOPV." (PMID 24421914, 2014). "Further chemokine gene expression studies in brains of ECM-susceptible mice confirmed that CXCL10, CXCL9 and CCL5 and to lesser extent CCL2, CCL7, CCL3, CCL4 and CXCL2 are upregulated during infection with P. berghei ANKA." (PMID 24476686, 2014). "The median CXCL9 concentration in the serum increased from 105 pg/mL to 755 pg/mL, 1110 pg/mL, and 521 pg/mL at 2, 4, and 6 weeks post-infection, respectively (p<.001, <.001, and <.05, respectively, compared to non-infected controls)." (PMID 23940724, 2013). "Following infection in vitro, C. parvum sporozoites induce the production of CXCL9 and CXCL10 in IEC by a yet-unidentified mechanism." (PMID 24367259, 2013). "The infection also activates the transcription of Cxcl1, Cxcl2 that regulate the influx of PMNs, Cxcl3 that controls migration of monocytes, Cxcl9 the Th1-attracting protein and the interferon-γ - inducible protein-10 (IP-10/Ccxl10)." (PMID 24148319, 2013). "The mRNA expression of Cxcl9, slightly increases in response to L. major during early infection in BMdM derived from the two mice strains." (PMID 24148319, 2013).
infection (continued). "These gene lists also featured a number of inflammatory cytokines and chemokines involved in chemotaxis of myeloid and lymphoid cell types to the sites of infection (Ccl4, Ccl5, Ccl7, Ccl12, Cxcl9, Cxcl10)." (PMID 23853600, 2013). "The production of IFN-γ and CXCL9 by WT and IL-10−/− liver leukocytes was increased as infection progressed." (PMID 22880122, 2012). "In particular, we showed that IFN-γ-dependent chemokines (CXCL9/10) were strongly induced, as shown by others, and increased during the course of infection, as well as their receptor CXCR3." (PMID 22457760, 2012). "Accordingly, expression of Cxcl9, Cxcl10, and Cxcl16 was increased earlier, at 14 days after infection in lungs of C57BL/6 compared with C3HeB/FeJ mice, with expression most pronounced in macrophages, conventional dendritic cells (cDCs), and, in the case of Cxcl10, neutrophils." (PMID 40986319, 2025). "The most significantly upregulated gene upon PCN033 infection was Cxcl9, followed by Cxcl11." (PMID 41295668, 2025). "Similarly, CXCL9 levels were elevated in the infection group from day 3 until day 9 p.i., indicating a temporal pattern in the host immune response." (PMID 40760251, 2025). "On the other hand, IFNγ may induce macrophages to release chemokines CXCL9, 10, and 11 to attract B and T lymphocytes to the sites of infection." (PMID 40762872, 2025). "Furthermore, PG-1 significantly downregulated key immune-associated genes, Cxcl9, Cxcl11, Tnfrsf9, Vdr and Ramp3, which were among the top 10 significantly upregulated genes post PCN033 infection." (PMID 41295668, 2025). "The three most upregulated chemokines during infection were Ccl5, Cxcl9, and Cxcl10." (PMID 40635167, 2025). "Increased chemotactic signals, such as Cxcl9 and Cxcl10, at the base of the muscularis might be responsible for the accumulation of short-lived effector cells observed in the few days after infection." (PMID 39843748, 2025). "Of the six leopards with unknown infection status, three had positive CXCL9 results along with CXCL10 upregulation." (PMID 37727792, 2023). "In addition, we measured the expression levels of CXCR3, a marker known to facilitate homing to inflamed lung mucosae during infection via CXCL9 and CXCL1039,43,44." (PMID 37573434, 2023). "CXCL9/MIG plays a role in recruiting immune cells to sites of infection and inflammation." (PMID 37949890, 2023). "These chemokines, including CXCL9, -10, and -11, all function to recruit Th1 cells, suggesting there could be a reduced Type-1 response by infants during infection." (PMID 35406717, 2022). "Notably, genes encoding the Th1-attracting chemokine CXCL9 (Cxcl9) and the CCL2 receptor, CCR2 (Ccr2), were found to be downregulated in both mouse strains after infection, but this downregulation was greater in BALB/c macrophages." (PMID 33617537, 2021). "The levels of CXCL-9 were 41 times higher in the 64 kDa immunized group and 6-fold higher in the case of 36 kDa, although the levels for 29 kDa remained at only 3.5-fold higher, but were better compared to the infection alone group (0.8-fold change)." (PMID 34696166, 2021). "However, once infiltrated into the SG, CD4 T cells are attracted to sites of infection by CXCL9/10 gradients, produced by either myeloid or epithelial cells of the SG." (PMID 34959486, 2021). "Indeed, we saw enhanced CXCL9 responses in pMT-10 mice after day 25 of infection, the time at which these mice begin displaying higher M. tuberculosis loads than B6 mice." (PMID 34554927, 2021). "In addition, infant AMφs produced significantly more CXCL8 (q = 0.007) in culture supernatants at 24 h post-infection, but significantly less CXCL9 (q = 0.007) compared with adult AMφs." (PMID 32265931, 2020). "In addition, increased concentrations of CXCL9 were detectable 5 days after (re-)infection in skin lysates of primed mice compared to naïve controls." (PMID 32639232, 2020).
infection (continued). "The chemokine CXCL9 attracts Th1 cells and inhibits the migration of Th2 cells to the site of infection and may thus improve the vaccine efficacy for intracellular infections, a desired feature for effective vaccines." (PMID 32957508, 2020). "In addition, both MO-DCs and pDCs produced CXCL10 chemokine on days 4, 9, 12, and 20 after infection, but only MO-DCs produced CXCL9 and CXCL10 at the same time." (PMID 32574175, 2020). "We noticed an increase in CXCL10 and CXCL9 expressions during infection compared to naïve hearts." (PMID 32574175, 2020). "Furthermore, we demonstrated that specific ligands for both CCR6 and CXCR3 (MIP‐3α and CXCL9/10, respectively) were expressed in the trachea after infection, suggesting their involvement in the recruitment of γδ T cells." (PMID 31777067, 2020). "Furthermore, Mφ of previously infected mice had increased expression of Stat1 and Cxcl9 1 and 5 days after (re-)infection." (PMID 32639232, 2020). "In addition to enhanced CXCR3 expression, we evaluated the concentrations of the CXCR3 ligands IP-10/CXCL10 and MIG/CXCL9 in the serum of mice at days 0, 6, 8, 10, 12, and 14 after infection." (PMID 31356587, 2019). "Likewise, CXCL9 and CXCL11 have been associated with infections such as rhinovirus and influenza virus." (PMID 30467502, 2018). "After in vitro infection with L. braziliensis, CL patient neutrophils produced more reactive oxygen species (ROS) and higher levels of CXCL8 and CXCL9, chemokines associated with recruitment of neutrophils and Th1-type cells, than neutrophils from control healthy subjects (HS)." (PMID 27167379, 2016). "Examination of chemokine expression at memory showed that infection resulted in sustained upregulation of transcripts encoding for a variety of different chemokines, including CCL1, CCL2, CCL5, CCL8, CXCL9 and CXCL10 compared with control flank skin from the same animals." (PMID 27160938, 2016). "Among these genes, several encode chemokines (IL8, CXCL1, CXCL10, CXCL11, CXCL9, PF4, PPBP), a family of small proteins that play important roles in the immune system through leukocyte recruitment, cell communication and cell activation during infection." (PMID 26791855, 2016). "In the i.n. model, infection by vΔ169 caused enhanced production of several cytokines (IL-2, IL-6 and TNF-α) and chemokines (CCL11, CXCL9 and CXCL10) within 1 day p.i. and subsequent greater recruitment of macrophages and CD4+ and CD8+ T cells and increased lung weight." (PMID 26334635, 2015). "Additionally, antimicrobial activity of CXCL9 appears to play a key role in protection of mucosal surfaces against pathogen infection." (PMID 25643352, 2015). "Additionally, neutrophils recruited to the site of infection produce numerous cytokines and chemokines, including CXCL9, CXCL10 and CXCL11." (PMID 24646914, 2014). "CXCR3 and its ligands (CXCL9, CXCL10, and CXCL11) are undoubtedly linked to the Th1 pattern and constitute an inflammatory pathway that coordinates the immune responses at sites of infection and inflammation." (PMID 24586509, 2014). "The contribution of the surrounding liver tissue, however, was quite significant for other ones, e.g. IL-12, IFN-γ, IL-4 and IL-17A, at the early stage of infection; CXCL9, IL-4, IL-5, CCL17, at the middle stage; and IL-10 and TGF-β at the late stage of infection." (PMID 24637903, 2014). "Furthermore, the gene expression of the cytokines Cxcl9, Cxcl10, Cxcl11 and Ccl20 was increased early after infection." (PMID 25137043, 2014). "Similarly, we found significantly less percentages of CXCL9 - expressing monocytes in HSV-2 infected Fas and FasL-deficient mice at 3 day of infection (p≤0.01), but only in FasL-deficient mice at 7 day of infection (p≤0.05)." (PMID 23922974, 2013). "However, our findings with IFNγ−/− neonatal mice show that during the infection CXCL9 and CXCL10 upregulation was strongly IFNγ-dependent." (PMID 24367259, 2013).